RUNX2 (RUNX family transcription factor 2)
Diseases named in the same sentence as RUNX2 in open-access papers (continued):
Sharing a sentence is not in itself a finding about the gene and the disease.
triple-negative breast carcinoma (9 papers, 2014 to 2025). An invasive breast carcinoma which is negative for expression of estrogen receptor (ER), progesterone receptor (PR), and human epidermal growth factor receptor 2 (HER2). "This study demonstrates that RUNX2 expression significantly associates with triple-negative breast cancer." (PMID 24626992, 2014). "In this regard, RUNX2 is significantly associated with triple-negative breast cancer and patients with higher RUNX2 expression have poorer survival rates." (PMID 24626992, 2014). "In triple-negative breast cancer, RUNX2 silencing suppressed cancer cell proliferation, metastasis, and invasion as well as chemoresistance." (PMID 41511334, 2025). "Taken together, the proliferation, drug resistance, and anchorage-independent growth in triple negative breast cancer MDA-MB-231-Re cells were consistently impaired by RUNX2 knockdown." (PMID 36483054, 2022). "Of note, state-of-the-art renewal has indicated the oncogenic role of RUNX2 in multiple cancer types, which the expression pattern and regulatory mechanism during chemoresistance in triple negative breast cancer are largely indistinct." (PMID 36483054, 2022). "Strikingly, the proliferation, migration, invasion and chemoresistance of resistant cell lines in triple negative breast cancer was effectively suppressed by RUNX2 silencing, and the in vivo tumorigenicity was significantly weakened as well." (PMID 36483054, 2022). "To assess the influence of RUNX2 in the migration and invasion of triple negative breast cancer, we transduced lentivirus-mediated shRUNX2 into MDA-MB-231-Re cells (denoted as shRUNX2) to knockdown the endogenous expression of RUNX2." (PMID 36483054, 2022). "For the purpose, we verified that RUNX2 knockdown was adequate to inhibit the in vitro proliferation, migration, invasion, and chemoresistance of resistant cells in triple negative breast cancer as well as the tumor growth in BALB/c nude mice." (PMID 36483054, 2022). "Overall, our data indicated the crucial role of RUNX2 in tumorigenesis during triple negative breast cancer." (PMID 36483054, 2022). "Its expression in triple-negative breast cancer cells is enhanced by the transcription factor RUNX2, and both, BSP and RUNX2 are under control of IGF-1 and TGFβ1." (PMID 30805306, 2019). "We envisage that future studies, using in vivo triple-negative breast cancer models will help to clarify the role of RUNX1 and RUNX2 in triple-negative breast cancer." (PMID 26489514, 2015). "We confirm RUNX2 as a gene that has a potentially important functional role in triple-negative breast cancer." (PMID 24626992, 2014). "MMP1 might play a critical role in mediating the tumor-promoting effect of RUNX2 in triple negative breast cancer cells." (PMID 36483054, 2022). "In one research report, it was illustrated that a reduction of miR-1305 in triple-negative breast cancer could enhance the expression of RUNX2 and facilitate cancer aggressiveness." (PMID 33292234, 2020). "Collectively, RUNX2 knockdown was adequate to inhibit EMT and reduce the in vitro migration and invasion in the triple negative breast cancer resistant MDA-MB-231-Re cells." (PMID 36483054, 2022). "Furthermore, with the aid of transcriptomic analysis and ChIP-qRT-PCR assay, we identified that RUNX2/MMP1 axis functioned a crucial role in the malignant progression and poor prognosis in triple negative breast cancer." (PMID 36483054, 2022). "To further illustrate the molecular mechanism of MMP1 and RUNX2 in TNBC, we initially examined the expression pattern of RUNX2 and MMP1 in the SUM-149 and MDA-MB-231 triple negative breast cancer cell line and the MCF-7 non-triple negative breast cancer cell line." (PMID 36483054, 2022). "Consistently, we found that the mRNA expression levels of RUNX2 and MMP1 revealed similar expression pattern, and in particular, those in triple negative breast cancer cell line were significantly higher than in non-triple negative breast cancer cell line." (PMID 36483054, 2022).
triple-negative breast carcinoma (continued). "Furthermore, with the aid of transcriptomic and bioinformatic analyses, we found MMP1 was highly expressed in triple negative breast cancer (TNBC) and showed a strong correlation with the poor prognosis of the patients, which was consistent with the expression pattern of RUNX2." (PMID 36483054, 2022).
hyperlipidemia (8 papers, 2016 to 2025). "Also, oxidative stress and oxidized lipids from hyperlipidemia or an abnormal dose of vitamin D promotes VSMC calcification by upregulating Runx2." (PMID 32192106, 2020). "Implants were tightly integrated with the surrounding dense new bone tissues, and ALP as well as Runx2 mRNAs were enhanced in miR-29a-3p overexpressed and hyperlipidemia rats, while little peri-implant bone tissue existed, ALP and Runx2 deregulated on miR-29a-3p inhibited rats." (PMID 30386554, 2018). "Lower Runx2 expression and higher TRAP expression were found in both diet-induced and genetic hyperlipidemia mice, indicating decreased osteoblastic functions and increased osteoclastic functions in these mice." (PMID 38089619, 2023). "Previous studies have reported that statins may improve hyperlipidemia and enhances femoral head neovascularization through suppresses PPARγ expression and activates Wnt3a/LRP5/b-catenin/RUNX2 signaling pathway in steroid-induced animal models." (PMID 32509867, 2020).
pulmonary fibrosis (8 papers, 2018 to 2025). Chronic progressive interstitial lung disorder characterized by the replacement of the lung tissue by connective tissue, leading to progressive dyspnea, respiratory failure, or right heart failure. "Taken together, Runx2 exhibits diverse functions in the fibrosis process of different organs and even exhibit a hallmark of cell‐specific expression in lung fibrosis." (PMID 37403784, 2023). "In addition, RUNX2 has been reported to be linked to profibrotic signaling contributing to pulmonary fibrosis and invasion as well as in inflammation-oriented lung diseases." (PMID 41299665, 2025). "Positive regulation of ERK1 and ERK2 cascades modulates cell differentiation in contexts such as pulmonary fibrosis and chondrogenesis via transcription factor phosphorylation (e.g., Runx2); however, its functional impact on ovine adipogenesis remains uncharacterized." (PMID 41179500, 2025). "Thus, the increased RUNX2 expression in LC-EVs-treated cells further highlights the role of RUNX2 in profibrotic signalling and pulmonary fibrosis." (PMID 41299665, 2025). "Targeting RUNX2 pathways in a cell-specific manner may hold promise as a therapeutic approach for pulmonary fibrosis." (PMID 40356603, 2025). "However, the authors also reported that RUNX2 mRNA was significantly increased in a whole-lung homogenate from idiopathic pulmonary fibrosis patients/pleomycin-lung fibrosis rat models compared with its expression in the relevant controls." (PMID 29954457, 2018). "Moreover, Runx2 expression is highly increased in fibrotic alveolar epithelial type II (AT II) cells, but not affected in fibroblasts during the process of pulmonary fibrosis, suggesting that the role of Runx2 in regulating fibrosis‐associated genes is opposite between AT II cells and fibroblasts." (PMID 37403784, 2023). "Two of the six transcriptional regulators (RUNX2 and TWIST1) are deregulated in other lung diseases (LD) (i.e., idiopathic pulmonary fibrosis (IPF) and pulmonary arterial hypertension (PAH))." (PMID 36551878, 2022).
esophageal cancer (7 papers, 2018 to 2022). A primary or metastatic malignant neoplasm involving the esophagus. "RUNX2 plays an oncogenic role in esophageal carcinoma by activating the PI3K/AKT1 and extracellular-regulated kinase signaling pathways." (PMID 33365318, 2020). "Runx2 plays an oncogenic role in esophageal carcinoma by activating the PI3K/AKT and ERK signaling pathways." (PMID 32913476, 2020). "It has been shown recently that the knockdown of RUNX2 in esophageal carcinoma cells significantly inhibits cell migration and invasion, suppresses tumor formation in vivo, and increases apoptosis." (PMID 30463392, 2018). "In addition, Runx2 has been shown to promote proliferation and migration of esophageal cancer cells." (PMID 35342401, 2022). "According to some findings, RUNX2 may play an oncogenic role in esophageal carcinoma by activating the PI3K/AKT and ERK pathways." (PMID 36140838, 2022). "Runx2 knockdown leads to cell proliferation arrest and apoptosis in esophageal carcinoma cells." (PMID 35342401, 2022). "Investigation indicates that RUNX2 has a possible oncogenic role in esophageal carcinoma." (PMID 31528308, 2019).
Hypertension (7 papers, 2011 to 2024). The presence of chronic increased pressure in the systemic arterial system. "Indoxyl sulphate: Parallel to inducing vascular calcification, indoxyl sulphate administration to human VSMC or rats with hypertension or 5/6 nephrectomy increased the expression of CBFA1/RUNX2, ALP, BMP2 and osteopontin, while a reduction in α-SMA, SM22-α and/or SMTN expression could be observed." (PMID 33172085, 2020). "Hypertension leads to an increase in RANKL expression and reduces RUNX2, with a consequent imbalance in the bone metabolism." (PMID 37754885, 2023).
keloid (7 papers, 2019 to 2025). An irregularly shaped, elevated mark on the skin caused by deposits of excessive amounts of collagen during wound healing. "This consistently leads to a reduction of the CAV1 content in affected skin areas, causing the established hallmark of hypertrophic scarring (HTS) and keloids (KE), as well as overexpression of RUNX2, which promotes the formation of the cartilage-like hyalinated scar tissue." (PMID 41246307, 2025). "Microarray results from seven Japanese patients with keloids revealed that Runt-related transcription factor 2 (RUNX2) is an upstream regulator of ECM." (PMID 36532050, 2022). "The expression of miR-194-3p was lower in keloids, and MiR-194-3p was shown to target RUNX2 directly." (PMID 30956986, 2019). "A recent study investigated the use of Runx2 siRNA to knockdown Runx2 mRNA in hypertrophic keloid fibroblasts (HKFs) and found that si-Runx2 transfection significantly inhibited the biological functions of HKFs, including proliferation, migration, and extracellular matrix deposition." (PMID 39201463, 2024). "MiR-194-3p and RUNX2 may become new targets for the prevention and treatment of keloids." (PMID 30956986, 2019). "However, there are few reports on the role of RUNX2 in keloids." (PMID 30956986, 2019). "For example, the SNHG1/miR-320b/CTNNB1 axis modulates fibroblast migration during keloid formation, while GNAS-AS1 knockdown reduces keloid growth via the miR-188-5p/RUNX2 pathway." (PMID 40943318, 2025). "In keloid fibroblasts, reduced CAV-1 leads to upregulation of the transcription factor RUNX2, which is a potential regulator of increased ECM production in keloids and is associated with fibrosis." (PMID 35614943, 2022).
lymph node metastasis (7 papers, 2007 to 2026). "In addition, in head and neck cancer, down-regulated miR-376c-3p leads to runt-related transcription factor 2 gene (RUNX2) deregulation and is associated with lymph node metastasis." (PMID 29482431, 2018). "RUNX2 has been associated with Dukes staging, including liver and lymph node metastasis." (PMID 29137387, 2017). "In oral cancer patients, a high RUNX2 level was correlated with lymph node metastasis." (PMID 37108164, 2023). "RUNX2 expression has been correlated with tumor size, tumor stage, lymph node metastasis, and shorter postoperative survival time, suggesting that it might become a novel prognostic marker in NSCLC." (PMID 36551878, 2022). "Overexpression of RUNX2 in NSCLC is significantly correlated with tumor size, stage, and lymph node metastasis." (PMID 36510562, 2022). "Correlation analysis of Runx2 mRNA expression with TNM staging of PDAC patients revealed a tendency for decreased median Runx2 mRNA levels in PDAC patients with lymph node metastasis compared to PDAC patients without lymph node metastasis (P=0.7; data not shown)." (PMID 17876328, 2007).
metastatic disease (7 papers, 2010 to 2022). "We and others have shown that Runt-related transcription factor-2 (Runx2) promotes metastatic tumor growth-associated bone loss." (PMID 35884497, 2022). "RUNX2 is an osteogenic transcription factor that regulates cell proliferation and is associated with metastatic disease in patients with prostate cancer." (PMID 34552244, 2021). "Moreover, increased nuclear staining of RUNX2 was an independent marker of metastatic disease in human CaP." (PMID 24983969, 2014). "Currently ongoing studies that address the biochemical basis for the relationships among RUNX2, cell migration and metastatic disease suggest that RUNX2 may regulate the expression of a distinct set of genes required for cell motility and adhesion (unpublished observations)." (PMID 21029421, 2010). "We found six genes such as SPP1, VEGFA, POSTN, RUNX2, CD44, and FOXO1 that were consistently overexpressed in patients with bone metastasis compared to non-metastatic tumors." (PMID 36424413, 2022). "RUNX2 gene expression showed negative correlation with SNAI2 genes in primary and metastatic tumors." (PMID 34792282, 2022).
liver cancer (6 papers, 2016 to 2023). An epithelial or non-epithelial malignant neoplasm that arises from the liver. "YAP, which was a downstream factor of Hippo signaling, interacts with RUNX2 to play an oncogenic role in liver cancer." (PMID 27007162, 2016). "In liver cancer, our results showed that RUNX1 but not RUNX2 or RUNX3 was upregulated in tumor tissue in comparison with normal tissue." (PMID 32746865, 2020).
liver fibrosis (6 papers, 2023 to 2025). "This study investigates the molecular mechanism underlying HBV-induced liver fibrosis, focusing on the role of RUNX2 in regulating integrin beta-like 1 (ITGBL1), a key factor in fibrogenesis." (PMID 40287769, 2025). "Furthermore, 3,5‐diethoxycarbonyl‐1,4‐dihydrocollidine (DDC)‐induced or methionine‐choline‐deficient (MCD)‐induced liver fibrosis mice models were established to evaluate the role of Runx2 in liver fibrosis caused by other aetiologies." (PMID 37403784, 2023). "In liver fibrosis, RUNX2 has been reported to activate hepatic stellate cells (HSCs) by upregulating Itgav expression and functioning as a transcriptional inhibitor of SLC27A5, resulting in the buildup of cholic acid and subsequent activation of HSCs." (PMID 40287769, 2025). "Another study demonstrated that RUNX2 promotes liver fibrosis and HSC activation by increasing unconjugated cholic acid through binding the SLC27A5 promoter and downregulating SLC27A5." (PMID 40287769, 2025). "In this study, we identified a novel regulatory pathway through which hepatitis B virus (HBV) induces liver fibrosis via the RUNX2-mediated upregulation of integrin beta-like 1 (ITGBL1), which can be blocked by Vitamin D3." (PMID 40287769, 2025). "Our results similarly demonstrate that RUNX2 promotes liver fibrosis in the context of HBV expression." (PMID 40287769, 2025). "Taken together, our findings demonstrate that RUNX2 is a crucial regulator in liver fibrosis by activating HSCs." (PMID 40287769, 2025). "The use of a selective p38 mitogen-activated protein kinase (MAPK)inhibitor has been shown to ameliorate liver fibrosis through the downregulationof RUNX2 in rat models, indicating its pivotal role in fibrogenic processes." (PMID 39484128, 2024). "For instance, RUNX2 activation inhepatic stellate cells has been shown to drive liver fibrosis by upregulatingintegrin alpha-V (Itgav) expression." (PMID 39484128, 2024). "Previous studies have shown that runt‐related transcription factor 2 (Runx2) is associated with the development of non‐alcoholic fatty liver disease, while its specific role in HSC activation and hepatic fibrosis remains elusive." (PMID 37403784, 2023). "Knockdown or overexpression of Runx2 expression in HSC significantly inhibited or promoted liver fibrosis induced by various factors." (PMID 37403784, 2023). "Collectively, these findings indicated that Runx2 expression was gradually increased during the liver fibrosis process, and presented potentially cell‐specific expression in liver tissues." (PMID 37403784, 2023). "We identified Runx2 as a HSC‐specific protein during liver fibrosis, which is essential for the regulation of HSC activation." (PMID 37403784, 2023). "Histologically, CWHM‐12 significantly reduced liver fibrosis measured by collagen deposition (Masson staining and collagen I staining) and α‐SMA staining, and importantly, αv integrins inhibition significantly blocked Runx2‐aggravated liver fibrosis." (PMID 37403784, 2023). "HSC‐specific knockdown of Runx2 alleviated CCl4‐induced, DDC‐induced or MCD‐induced liver fibrosis, while overexpression of Runx2 by HBAAV‐Runx2 injection exacerbated CCl4‐induced liver fibrosis." (PMID 37403784, 2023). "To investigate the role of Runx2 in liver fibrosis, we first explored Runx2 expression in the GEO database." (PMID 37403784, 2023). "Taken together, our findings demonstrate that Runx2 facilitates liver fibrosis by promoting HSC activation." (PMID 37403784, 2023). "Targeted knockout of Runx2 expression in HSC or intrahepatic overexpression of Runx2 significantly inhibited or promoted liver fibrosis induced by various factors." (PMID 37403784, 2023). "To determine the role of Runx2 in the process of liver fibrosis in vivo, we first utilised lenti‐shRNA to knock down Runx2 in mice treated with CCl4, and the data indicated that Runx2 knockdown alleviated CCl4‐induced liver fibrosis." (PMID 37403784, 2023).